CTLA4 (cytotoxic T-lymphocyte associated protein 4)
Diseases named in the same sentence as CTLA4 in open-access papers (continued):
Sharing a sentence is not in itself a finding about the gene and the disease.
Autoimmunity (continued). "However, CTLA-4 antibodies may lead to autoimmunity, due to its role in maintaining self-tolerance." (PMID 33256070, 2020). "Activation of co-inhibitory receptors, including CTLA-4, PD-1, LAG-3, TIM-3, and TIGIT, induce immune tolerance, therefore their stimulation would be beneficial in autoimmune disorders." (PMID 30564191, 2018). "Abatacept is a protein formed by the fusion of the Fc domain of IgG1 to the extracellular domain of CTLA4, thereby mimicking the binding of CTLA4 to CD80/CD86 and helping to tamp down autoimmunity." (PMID 28848545, 2017). "Function of CTLA-4 and PD-1 in the immune network and the impact of immune-checkpoint inhibitors anti-CTLA-4 and/or anti-PD-1 on examples of tumor immunity and autoimmunity." (PMID 24904570, 2014). "A combined blockade of CTLA4 and PD1-PDL1 will in all probability shift the balance from an effective immune response towards autoimmunity." (PMID 24586872, 2014). "The agents regulating the signals through coinhibitory molecules including CTLA-4, PD-1, and BTLA have the potential to regulate autoimmunity and responses to tumors and chronic infections." (PMID 22997525, 2012). "In the current study, CTLA4, FOXP3 and HLA were selected because T lymphocytes play a major role both in tumor immunity and autoimmunity and these genes are well known to directly or indirectly affect T cell function." (PMID 22911710, 2012). "However, neurologic manifestations should be taken into consideration in the diagnostic work-up of subjects carrying symptoms commonly related to CTLA4 haploinsufficiency, such as CVID and multi-organ autoimmunity." (PMID 40149457, 2025). "In contrast to PD-1 and CTLA-4, it has been determined that the loss of LAG-3 alone does not lead to the development of autoimmunity in non-autoimmune-prone mice." (PMID 38390331, 2024). "CTLA4 was an excellent candidate gene for an autoimmune disorder as a negative costimulatory molecule, present as a ‘second signal’ modulating T cell receptor activation in response to MHC-antigen presentation at the immunological synapse." (PMID 38108994, 2024). "In this context, it is also interesting that we describe a new patient with a CTLA4 defect (#116), without any sign of autoimmunity or autoinflammation, displaying only recurrent infections and splenomegaly." (PMID 38792965, 2024). "Recent reports demonstrate that Tregs can control costimulation-blockade-resistant immune responses in autoimmunity and transplantation if the negative effects of CTLA4-Ig on the Treg compartment are compensated." (PMID 38830846, 2024). "Importantly, MALT1 protease activity is required to maintain high expression of CTLA-4 on Treg cells and it was shown that even a moderate decrease in CTLA-4 expression can lead to autoimmunity." (PMID 36761777, 2023). "The conditional ablation of Ctla4 in adult Treg cells protected mice from autoimmunity, supporting the notion that CTLA-4 is a negative regulator of Treg cell expansion." (PMID 37197667, 2023). "This naturally led to the question of why treatment with CTLA-4:Ig in RA, does not result in a greater increase in their cancer risk when blocking CTLA-4 in cancer results in autoimmunity." (PMID 35784333, 2022). "The main role attributed to PD-1, as opposed to CTLA-4, is the limitation of T cell activity in peripheral tissues when there is an inflammatory response against infections, as well as limiting autoimmunity." (PMID 35145371, 2022). "As key and well-known regulatory immune checkpoint molecules, programmed death-1 (PD-1) as well as its ligand PD-L1 checkpoint pathway, in addition to immune checkpoint genes, including CTLA-4 and LAG3 play important roles in maintaining the balance between immune tolerance and autoimmunity." (PMID 35847354, 2022). "Consequently, anti-CTLA-4 antibodies probably lead to reduced CD80/86 signaling in DCs, thus decreasing self-tolerance and increasing autoimmunity." (PMID 36263134, 2022).
Autoimmunity (continued). "We present case 1 (CTLA-4 haploinsufficiency) and case 2 (CTLA-4 insufficiency-like phenotype) manifesting with severe autoimmunity including cytopenia and involvement of the central nervous system (CNS), lung, and gut and variable impairment of humoral responses." (PMID 36636328, 2022). "The role of autoimmunity in ICI-induced (anterior) hypophysitis is also sustained by detecting autoantibodies against cells secreting TSH, FSH, and ACTH in patients with anti-CTLA4-induced hypophysitis." (PMID 35205804, 2022). "In particular, Ctla4-null mice develop fatal autoimmunity early on in life, whereas their Ctla4+/− littermates do not develop features of autoimmunity." (PMID 33996698, 2021). "This probably suggests that the pathogenesis of autoimmunity is heterogeneous with many disorders not relying on PD1 or CTLA4 pathway." (PMID 34208218, 2021). "However, only 100% of CTLA4, PRKCD, TET2 and NRAS/KRAS reported patients had an ALPS-like presentation, while the autoimmunity and lymphoproliferation combination resulted rare in other genetic defects." (PMID 34447369, 2021). "This is a significant finding as CTLA-4 is involved in negative signaling and plays a pivotal inhibitory role in T cell anergy and prevention of autoimmunity." (PMID 34093553, 2021). "Autoimmunity-related risk variants in protein tyrosine phosphatase non-receptor type 22 (PTPN22) and cytotoxic T lymphocyte associated protein 4 (CTLA4) genes were found to be associated with infection-triggered ME/CFS in a recent study." (PMID 33889154, 2021). "CTLA-4 is upregulated on the T-cell membrane shortly after T-cell activation, and the binding of CTLA-4 to B7 molecules provides inhibitory signals for the T cell and induces Treg responses, thereby limiting inflammation and preventing autoimmunity." (PMID 34124192, 2021). "By contrast, mice with ablation of CTLA-4 expression during adulthood developed severe, but not fatal, autoimmunity." (PMID 33692958, 2021). "It has been shown that CTLA-4 knockout results in massive lymphocytic infiltration and the development of lymphoproliferative diseases; this demonstrated the major role of CTLA-4 in the control of autoimmunity and T cell activation." (PMID 33272321, 2020). "In macaques, treatment with CTLA-4 or a combination of CTLA-4 + PD-1 antibodies resulted in induction of plasma autoantibodies to SCL-70, RNP and Histone proteins commonly observed in human autoimmunity." (PMID 32075963, 2020). "This indicates that in vivo suppression mediated by Treg cells through CTLA‐4 participates in the prevention of antitumor immune responses and with CTLA‐4 haploinsufficiency, of autoimmunity and/or immune dysregulation in the skin, the gut and in some endocrine organs." (PMID 29484183, 2018). "CTLA-4 has a higher binding affinity for B-7 ligands than CD28, and CTLA-4 can bind to B7 and displace CD28, leading to attenuation and termination of T cell responses and establishment of tolerance, to minimize the development of autoimmunity." (PMID 28545567, 2017). "This strategy not only prevents potential toxicity of anti-PD-1 or CTLA-4 administration (e.g., opportunistic autoimmunity) but it also would not interfere with normal homeostatic functions of these molecules within the body." (PMID 29312333, 2017). "Although the mechanism by which CTLA-4 enhances the immunosuppressive function of Tregs is not known, Tregs specific CTLA-4 knockout or blockade significantly inhibits their ability to regulate both autoimmunity and antitumor immunity." (PMID 25823653, 2015). "The first surprise in the data is that punctual ablation of the CTLA-4 gene in 7-week old mice failed to trigger spontaneous autoimmunity, contrasting with the situation following germline deletion." (PMID 26596798, 2015). "Unregulated availability of ligands, in mice lacking CTLA-4, results in unfettered T cell responses that culminate in lethal autoimmunity." (PMID 24470500, 2014).
Autoimmunity (continued). "Short blockade of CTLA-4 during priming of the immune response has lasting effects, suggesting that failure in the regulation of CTLA-4 would have long-lasting impact on immune responses including autoimmunity." (PMID 24023412, 2013). "The CTLA4 gene should be recognised as the first major known non-HLA locus of human autoimmunity and that its role in the pathogenesis of HT is rather general and non-specific." (PMID 15762980, 2005). "Importantly, these mice did not succumb to cytokine storm or systemic autoimmunity, as seen in Ctla4 or Pdcd1 null mice, and had limited inflammation in extraneous tissues." (PMID 39247203, 2024). "Here, we address the hypothesis that targeting CTLA-4 or PD-1 and its ligand PD-L1 critically impacts the function of Tfh cells in patients that receive these ICIs, thereby providing a link between ICI treatment and the development of secondary autoimmunity." (PMID 34112740, 2021). "In case of T1D, another pathway might be involved: Inhibition of EHMT2 has been shown to enhance CTLA4 and FOXP3 expression in regulatory T cells, both are markers of regulatory T cell function needed to maintain tolerance and prevent autoimmunity." (PMID 34220961, 2021). "However, the frequencies of CTLA-4 and HLA-DRB1 were not significantly different between the autoimmune FXIII deficiency cases and those reported by the database." (PMID 34506591, 2021). "Theoretically, TIGIT-blockade may be an interesting alternative for CTLA-4 blockade, because TIGIT knockout mice do not develop autoimmunity, while CTLA-4 knockout mice die within 2-3 weeks due to severe autoimmunity." (PMID 34367161, 2021). "As the population of CVIDid patients with low CTLA4 + CD27 + Tregs represented a mix of patients with pulmonary inflammation but also other organ-specific autoimmunity (data not shown), abatacept may be efficacious in other CVIDid patients as well." (PMID 34247288, 2021). "In addition, CTLA-4 may also play a role in PI3K signals as well as in regulatory T-cell function, autoimmunity, and cancer." (PMID 34671350, 2021). "The use of anti-CTLA-4 antibodies in monotherapy and in combination with anti-PD-1/PD-L1 antibodies have been discredited, due to the lack of significant clinical response and high incidence of autoimmunity." (PMID 33256070, 2020). "In the absence of a competently functioning CTLA-4 pathway, autoimmunity ensues." (PMID 31156616, 2019). "Thus, it is conceivable that patients with a high number of autoantibodies and hence a high level of autoimmunity may be more responsive to therapies targeting B- and T-lymphocytes such as the anti-CD20 antibody rituximab or the CTLA4-Ig construct abatacept." (PMID 29740454, 2018). "Final evidence of abrogation of autoimmunity was that vitiligo and white hair at the injection site that were observed in three of seven mice that received CTLA4 and PD1 mAbs was not seen with mice that also received OX40L and CD30L blockade (none of seven mice)." (PMID 28646041, 2017). "Once a T cell is activated, CTLA-4 (CD28 homolog) is expressed on its surface to block the costimulatory signal through its greater affinity for CD80/86, playing an important role in self-tolerance and therefore limiting autoimmunity under normal homeostatic conditions." (PMID 27472273, 2016). "CTLA-4, expressed exclusively on T-cells, acts as a negative co-stimulatory signal, inhibiting T-cell activation and proliferation to maintain self-tolerance and protect from autoimmunity." (PMID 26337719, 2015). "In conclusion, the lack of association between SNPs in the genetic master switches of autoimmunity, PTPN22 and CTLA-4, suggests that regardless of the strong linkage with HLA-B*27, AAU should be regarded as an autoinflammatory rather than an autoimmune condition." (PMID 19180256, 2009).
Autoimmunity (continued). "Finally, prior studies have shown PD-1 blockade to be the primary driver of accelerated autoimmunity in adult mice, but ICI-T1DM can also develop in patients with cancer who are treated with combination ICI regimens (e.g., anti–PD-1 + anti-cytotoxic T lymphocyte antigen [CTLA-4])." (PMID 40626363, 2025). "Several negative immunoregulators, such as CTLA4, PD1, and its ligands, modulate the immune response to maintain homeostasis and prevent hyperactivation or autoimmunity." (PMID 40143377, 2025). "Therefore, treatment targeting CTLA-4 or PD-1 and their ligand PD-L1 may significantly affect TFH cell function in patients receiving immune checkpoint inhibitors(ICIs) therapy, providing a link between ICI therapy and the development of secondary autoimmunity." (PMID 40027134, 2025). "While the lack of CTLA-4 gene can result in multi-organ lymphocytic infiltration, Treg cell defect and autoantibody production, CTLA-4 blockade did not induce substantial autoimmunity." (PMID 36949956, 2023). "Decreased or absent CTLA-4 activity permits uninhibited T-cell activity and a prolonged, unregulated immune response, making CTLA-4 an attractive candidate gene for autoimmunity." (PMID 22242199, 2012). "In autoimmune Addison’s disease (AAD), candidate-gene and GWAS data converge on HLA-DR3/DR4 with replicated non-HLA signals (CTLA4, PTPN22, BACH2, SH2B3) and common AIRE effects, extending an “AIRE dosage” concept from rare monogenic APS-1 into common, complex autoimmunity." (PMID 41465179, 2025). "Interestingly, compared to CTLA-4 knockout mice, VISTA knockout mice exhibit no signs for severe autoimmunity pointing out, that other inhibitory receptors compensate for loss of VISTA." (PMID 28073373, 2017). "Furthermore, excellent antitumor immune responses can also be achieved using combinations of Abs that block CTLA4, PD1, OX40, and CD30 ligands, without CD4 T cell–driven autoimmunity." (PMID 28646041, 2017). "Firstly, a pilot study performed by Small and colleagues have concluded that blocking of CTLA-4 with human anti-CTLA-4 antibody; ipilimumab in patients with CRPC has PSA-modulating effects, is well-tolerated, and does not lead to significant clinical autoimmunity." (PMID 22746994, 2012).
lung cancer (390 papers, 2010 to 2026). A malignant neoplasm involving the lung. "It is well established that antibodies targeting PD-1, its ligand PD-L1, or cytotoxic T lymphocyte-associated protein-4 (CTLA-4) represent an advancing therapeutic approach for lung cancer." (PMID 41011170, 2025). "Among the most intensively studied pathways in lung cancer immunotherapy are the programmed death-1 (PD-1)/programmed death-ligand 1 (PD-L1) axis and the cytotoxic T-lymphocyte-associated protein 4 (CTLA-4) pathway." (PMID 41262872, 2025). "CDCA3 expression correlates with immune exhaustion markers such as PD-1 and CTLA-4, and is associated with increased immune infiltration and poor outcomes in renal and lung cancers." (PMID 40963614, 2025). "In the context of lung cancer, the main ICIs include PD-1/PD-L1 (Programmed cell death protein 1/Programmed death-ligand 1) and CTLA-4 (Cytotoxic T-lymphocyte-associated protein 4) inhibitors." (PMID 41516258, 2025). "The efficacy of anti‐CTLA‐4 antibody (ipilimumab) plus anti‐programmed cell death 1 antibody (nivolumab) in treating advanced non‐small cell lung cancer (NSCLC) is impeded by an elevated risk of severe immune‐related adverse events." (PMID 38828610, 2024). "The programmed death receptor 1 (PD-1), programmed death receptor ligand 1 (PD-L1), and cytotoxic T lymphocyte-associated protein 4 (CTLA-4) pathways are common mechanisms by which lung cancer cells evade immune surveillance." (PMID 39439965, 2024). "Identified polymorphisms in PD-1, PD-L1, and CTLA-4 genes associated with clinical outcome of lung cancer patients." (PMID 38983267, 2024). "Recently, three studies on lung cancer showed that increased tumor expression of CTLA-4 was associated with better outcomes after tumor resection." (PMID 38611048, 2024). "Evidence suggests that immune checkpoint blockade immunotherapies targeting programmed cell death 1 (PD-1) or cytotoxic T-lymphocyte associated protein 4 (CTLA-4) are emerging as a new treatment option for lung cancer patients." (PMID 37955668, 2023). "Immune oncology treatments, such as immune-checkpoint inhibitors that target programmed cell death (PD)-1, PD-ligand (PD-L) 1, or cytotoxic T-lymphocyte-associated protein 4 (CTLA-4) are routinely used in lung cancer." (PMID 38450055, 2023). "CTLA-4 expression is also a key feature of highly suppressive Treg found to be enriched in tumour tissue of breast and lung cancer patients, which are associated with more aggressive disease." (PMID 36818683, 2023). "Currently, targeting cytotoxic T lymphocyte-associated protein 4 (CTLA-4) and PD-1 has provided superior anticancer effects in colorectal and lung cancer compared to conventional chemotherapy." (PMID 37860186, 2023). "Immune checkpoint inhibitors (ICIs), which evoke an antitumor T-cell response by targeting programmed cell death 1/programmed cell death ligand 1 (PD-1/PD-L1) or cytotoxic T-lymphocyte-associated antigen 4 (CTLA-4), have advanced the treatment of lung cancer." (PMID 35795657, 2022). "Till date, ipilimumab (IgG1 monoclonal antibody cytotoxic T-lymphocyte associated antigen 4, CTLA-4), pembrolizumab, nivolumab, cemiplimab, durvalumab and atezolizumab are approved for various indications in lung cancers." (PMID 36136862, 2022). "Currently, the most studied immune checkpoints in lung cancer mainly include cytotoxic T lymphocyte-associated antigen 4 (CTLA-4), programmed cell death receptor 1 (PD-1), and programmed cell death receptor ligand 1 (PD-L1), etc." (PMID 34163353, 2021). "Overall, the strength of association between CTLA-4 +49 A/G genetic polymorphism and lung cancer risk was evaluated using the pooled ORs and 95%CIs based on five genetic comparison models." (PMID 33819967, 2021). "Several publications have explored the relationship between cytotoxic T lymphocyte antigen-4 (CTLA-4) +49 adenine (A)/guanine (G) polymorphism and susceptibility of lung cancer, but the results remain controversial." (PMID 33819967, 2021).